GHR (growth hormone receptor)
Diseases named in the same sentence as GHR in open-access papers (continued):
Sharing a sentence is not in itself a finding about the gene and the disease.
diabetic nephropathy (4 papers, 2019 to 2024). "Conversely, studies have shown that a deficiency in growth hormone (GH) or the inhibition of GH receptor (GHR) activity can offer protection against diabetic nephropathy." (PMID 38673935, 2024). "In this study, GHR, VEGFA and EFEMP1 were identified as potential biomarkers for diagnosing and treating diabetic nephropathy." (PMID 37404805, 2023).
glioma (4 papers, 2016 to 2022). A benign or malignant brain and spinal cord tumor that arises from glial cells (astrocytes, oligodendrocytes, ependymal cells). "Consistent with our data, high levels of GH and GHR expression were also reported by others in glioma cell lines compared to normal brain tissue, further supporting the oncogenic role of GHR signalling in GBM." (PMID 35808822, 2022). "Role of JAK2 in Hormone-like Cytokine Signaling stood out because GHR (growth hormone receptor) and IRS1 (insulin receptor substrate 1) has been linked with glioma progression." (PMID 27669421, 2016). "Growth hormone receptor (GHR) expression is elevated in one third of patients with gliomas, and GHR signaling affects the expression of proteins involved in cell motility, enhancing cell migration, invasion, and proliferation in vitro and carcinogenesis, tumor growth, and tumor invasion in vivo." (PMID 36497459, 2022). "Moreover, GH, GHR, and IGF-I have been detected within the same glioma cell, suggesting autocrine/paracrine actions that could be related to the resistance and aggressive behavior of this type of cancer." (PMID 29373545, 2018).
hypothyroidism (4 papers, 2017 to 2023). Abnormally low levels of thyroid hormone. "WES analysis showed several variants in genes associated with short stature, GH deficiency and hypothyroidism including ACAN, GHR, RNPC3 and TSHR (Table-II)." (PMID 37680843, 2023). "In chickens, the treatment with propylthiouracil leads to hypothyroidism (T4 and T3 low) and this leads to lower GHR and IGF-1 mRNA expression in the liver." (PMID 35782551, 2022).
mild cognitive impairment (4 papers, 2019 to 2025). "Targeting genes implicated in both isolated and syndromic forms of cognitive impairment has allowed us to select two variants of interest in GHR and SLC19A3 genes." (PMID 34614013, 2021). "GHR promotes normal human postnatal growth and its deficiency or mutation may lead to utero and severe postnatal growth failure, intellectual impairment, microcephaly, and sensorineural deafness." (PMID 33891593, 2021). "A direct causality between the GHR gene variants and cognitive impairment has not been clearly established in the literature." (PMID 34614013, 2021). "For example, a Pennsylvania cohort identified four serum proteins—bone sialoprotein (BSP), osteomodulin (OMD), aminoacylase-1 (ACY1), and growth hormone receptor (GHR)—as PD biomarkers, yet these were not specific to PD when compared to ALS or mild cognitive impairment." (PMID 40699858, 2025).
Nephropathy (4 papers, 2019 to 2025). A nonspecific term referring to disease or damage of the kidneys. "Another study also showed that increased renal expression of the GHR was associated with nephropathy in poorly controlled type 1 diabetes." (PMID 37127580, 2023). "Elevated circulating growth hormone (GH) levels and increased renal expression of the GH receptor (GHR) are associated with nephropathy in poorly controlled type 1 diabetes." (PMID 33795655, 2021).
pancreatic cancer (4 papers, 2016 to 2024). "Here, we report the first preclinical validation of the postulated gemcitabine-sensitizing effect of GHR antagonism using two different GHRAs in cultured pancreatic cancer cells and mouse tumor xenografts." (PMID 39000545, 2024). "GH and GHR are expressed in mammalian pancreatic tissue in endothelial, epithelial, immune, and acinar cells, as well as in pancreatic tumor samples." (PMID 39000545, 2024). "Other studies have also shown that targeting GHR can control cancer metastasis, such as pancreatic cancer." (PMID 27825319, 2016). "Focused preclinical studies with human PDX models with dose-titration of combinations of GHRAs and selected antineoplastic agents and subsequent carefully designed human clinical trials are needed to validate the transformative prognostic potential of targeting GHR in pancreatic cancer." (PMID 39000545, 2024). "Finally, with the existence of an FDA-approved GHR antagonist and several others in active development targeting the full spectrum of GH action, our current study sets course in a feasible paradigm shift in the therapeutic augmentation of pancreatic cancer." (PMID 39000545, 2024). "In all of our cultured pancreatic cancer cell lines (human—PANC1 and BxPC3, mouse—LTPA and Pan02), GH and GHR protein expression is confirmed by western blot, while GHR protein expression is confirmed by immunocytochemistry as well, indicating an autocrine loop." (PMID 39000545, 2024). "Additionally, we observed that in the healthy human pancreas, RNA expression of GHR and IGF1 is positively correlated (Spearman correlation coefficient R = 0.43, p < 0.001) and the correlation further increases in pancreatic tumors (R = 0.71, p < 0.001)." (PMID 39000545, 2024).
prostate carcinoma (4 papers, 2014 to 2025). A carcinoma that arises from epithelial cells of the prostate gland. "The GH gene is coexpressed with the GHR gene in both normal and cancerous prostate cell lines and in human prostate tissue and is upregulated in many prostate cancers (Oncomine)." (PMID 25580121, 2014). "GHRs and GHR mRNA are abundantly present in normal prostate tissue and prostatic carcinoma cell lines." (PMID 25580121, 2014). "GH can activate heterodimers consisting of the GHR and the prolactin receptor (PRLR) in breast tissue, activating PRL signaling pathways, and GHR-IGF-1R heterodimers may potentiate GH signaling in prostate cancer cells." (PMID 25580121, 2014). "In the case of human prostate cancer cell lines (PC3 and LNCaP), 24‐hrs treatment with IGF1 and insulin reduced (or tended to reduce) the expression of IGF1R, INSR and GHR, whereas only insulin increased the expression levels of Igfbp3 in LNCaP cells." (PMID 28244645, 2017). "Additionally, increased GHR expression and autocrine/paracrine GH secretion in the tumor microenvironment (TME) have been reported in several different types of cancers, including colon, breast, pancreatic, gastric, and prostate cancers." (PMID 41515995, 2025). "The results of a recent study suggested that extracellular PRL enhanced NSCLC cell proliferation and promoted JAK2/STAT3 signaling activity through GHR, but not PRLR as previously reported in breast and prostate cancers." (PMID 34487971, 2021).
rectal cancer (4 papers, 2015 to 2022). A primary or metastatic malignant neoplasm that affects the rectum. "In rectal cancer, GHR overexpression was associated with poor response to radiotherapy." (PMID 35808822, 2022).
Sepsis (4 papers, 2007 to 2021). Sepsis is defined as life-threatening organ dysfunction caused by a dysregulated host response to infection. "Previously, we found that the decrease in serum IGF-I during sepsis was associated with the depression of growth hormone receptor (GHR) expression in the liver and increased circulating inflammatory cytokines." (PMID 34063554, 2021). "Our data showed that the mRNA expression of growth hormone receptor (GHR) was significantly decreased in the livers of sepsis mice when compared to those of healthy control mice (1 ± 0.17 vs. 5.0 ± 0.8, p < 0.01)." (PMID 31791247, 2019). "Firstly, it was shown that in sepsis mice the expression of GHR mRNA in liver was significantly suppressed." (PMID 31791247, 2019). "• Recent animal studies identified ghrelin, a stomach-derived ligand for the growth hormone receptor, as a mediator of various beneficial effects in sepsis." (PMID 20500817, 2010). "We found that nutrition and the route of nutrition in sepsis differentially influence circulating cytokine profiles and the expression of mRNA of SOCS proteins, of the GHR and of IGF-I." (PMID 17634149, 2007). "In established sepsis, nutrition and the route of administration of nutrition influences the circulating cytokine patterns and expression of mRNA of SOCS proteins, GHR and IGF-I." (PMID 17634149, 2007). "Nutrition increased the expression of mRNA of both IGF-I and the GHR, while these were not affected by sepsis." (PMID 17634149, 2007).
Anxiety (3 papers, 2014 to 2025). Intense feelings of nervousness, tension, or panic often arise in response to interpersonal stresses. "Notably, GH deficiency has been associated with increased anxiety and impaired fear memory in the context of post-traumatic stress disorder, consistent with GHR expression in the amygdala." (PMID 41226706, 2025). "Therefore, possible changes in anxiety were evaluated in CRH GHR KO mice during the open field and elevated plus maze tests." (PMID 34576072, 2021). "Nonetheless, CRH GHR KO mice did not exhibit evidence of changes in anxiety, as compared to control mice." (PMID 34576072, 2021). "The absence of GHR in CRH cells did not affect anxiety, circadian glucocorticoid levels or restraint-stress-induced corticosterone secretion and activation of PVH neurons in both male and female mice." (PMID 34576072, 2021). "However, GHR ablation in CRH neurons caused no significant alterations in metabolism, HPA axis, acute stress response or anxiety in mice." (PMID 34576072, 2021). "Subsequently, CRH-specific GHR knockout (KO) mice were generated and possible alterations in metabolism, ghrelin-induced food intake, basal and stress-induced corticosterone secretion, stress-induced activation of PVH neurons and anxiety were determined in male and female mice." (PMID 34576072, 2021). "In summary, GHR ablation, specifically in CRH-expressing neurons, does not lead to major alterations in metabolism, hypothalamic–pituitary–adrenal axis, acute stress response or anxiety in mice." (PMID 34576072, 2021).
atherosclerosis (3 papers, 2012 to 2024). A disease characterized by the build-up of fatty material and calcium deposition in the arterial wall resulting in partial or complete occlusion of the arterial lumen. "Also, ghrelin encoded by the GHR gene, a novel endogenous ligand for the growth hormone secretagogue receptor, was considered to exert a protective effect against atherosclerosis." (PMID 22761820, 2012). "We were able to confirm three additional proteins associated with CIMT using our age-sex adjusted model namely GFRA1, IGFBP2 and GHR, which have been all reported to be linked to CVD, mortality, and atherosclerosis." (PMID 38811951, 2024).
basal cell carcinoma (3 papers, 2017 to 2022). A carcinoma involving the basal cells. "The first identification of growth hormone receptor (GHR) RNA in human skin melanocyte cells dates back more than 20 years and has been followed by the discovery of autocrine levels of GH and IGF1, also present in normal skin and basal cell carcinoma." (PMID 35160191, 2022). "The presence of growth hormone receptor (GHR) RNA in human skin cells, especially melanocytes, was reported more than 20 years ago, followed by identification of autocrine levels of GH as well as IGF1 in normal and basal cell carcinoma." (PMID 28223541, 2017).
bladder cancer (3 papers, 2007 to 2025). "Transcriptomic profiling of The Cancer Genome Atlas bladder cancer cohort revealed that high tumoral GHR expression was associated with differential upregulation of genes involved in drug efflux, epithelial-to-mesenchymal transition (EMT), and extracellular matrix (ECM) remodeling." (PMID 40806252, 2025). "The MMPs with the highest correlation with GHR expression in both female and male patients with bladder cancer were MMP2 (rho = 0.472 (F), 0.457 (M)), MMP16 (rho = 0.464 (F), 0.509 (M)), and MMP23B (rho = 0.316 (F), 0.452 (M))." (PMID 40806252, 2025). "Collectively, our findings support a mechanistic role for GH signaling in driving therapy resistance and tumor aggressiveness in bladder cancer and suggest GHR antagonism as a potential therapeutic strategy to improve treatment outcomes." (PMID 40806252, 2025). "Using data from patients with bladder cancer in TCGA database, correlation analyses of differentially expressed mRNAs with respect to GHR mRNA expression in tumor samples were performed." (PMID 40806252, 2025). "To identify if bladder cancer may benefit from a treatment strategy that includes targeting GH action, we examined the relationship between GHR expression and patient survival." (PMID 40806252, 2025). "Many CYPs were also significantly inversely correlated with GHR expression in male patients with bladder cancer, and CYP7B1 was downregulated with increased GHR expression in both sexes." (PMID 40806252, 2025). "For further validation, Kaplan–Meier survival plots with GHR, GH1, IGF-1 receptor (IGF1R), or IGF1 as the reference gene were generated from TCGA database, including 405 patients with bladder cancer." (PMID 40806252, 2025). "Using transcriptomic data archived in TCGA obtained from 404 patients with bladder cancer, we found that, overall, GHR was not expressed as highly in bladder tumors as it was in normal bladder tissue taken from the same patients." (PMID 40806252, 2025).
breast tumors (3 papers, 2016 to 2020). "In conclusion, ccurrent research shows that H53 is a new inhibitor of GHR/PRLR which has potential as a reagent for the treatment of breast tumors." (PMID 33362552, 2020). "We prepared the GHR/PRLR dual-effect antagonist (H53) by anti-idiotypic antibody strategy, and found that H53 exhibits potential effects against breast tumors." (PMID 33362552, 2020). "In the current study, we found that H53 showed good antagonistic properties in vivo and in vitro, not only inhibiting GHR/PRLR-mediated intracellular signals, but also blocking breast tumor proliferation." (PMID 33362552, 2020).
cervical cancer (3 papers, 2019 to 2025). A primary or metastatic malignant neoplasm involving the cervix. "For example, one study found that over half of the tumor cells in 61% of cervical cancer patients express nuclear GHR, and high levels of nuclear GHR may act as a promoter of cervical cancer cell progression." (PMID 40313485, 2025). "A study that involved 33 young patients (<40 years) with cervical neoplasms has found that more than half of tumor cells express nuclear GHR in 61% of those patients and has suggested that a high degree of nuclear GHR may be a promoter of stimulating the progression of cervical carcinoma cells." (PMID 37064267, 2023).
Hyperglycemia (3 papers, 2013 to 2024). An increased concentration of glucose in the blood. "GHR-KO;RIP::IGF-1 mice are capable of inducing a greater transcriptional (or possibly translational, but probably not simply secretory) insulin action response to hyperglycemia than standard GHR-KO mice when challenged with a glucose load under AL-fed conditions." (PMID 25244225, 2014).
Hypoinsulinemia (3 papers, 2014 to 2024). A decreased concentration of insulin in the blood. "The low IGF-I levels is caused by nutritionally acquired hepatic GH resistance from intra-portal hypoinsulinemia, resulting in down-regulation of the hepatic GHR expression, as inferred from reductions in circulating levels of GHBP, and decreased GH binding." (PMID 39665021, 2024).
Impaired glucose tolerance (3 papers, 2020 to 2023). An abnormal resistance to glucose, i.e., a reduction in the ability to maintain glucose levels in the blood stream within normal limits following oral or intravenous administration of glucose. "Interestingly, disruption of GH signalling in growth hormone receptor (GHR)‐deficient mice leads to reduced β‐cell mass (due to decreased islet replication and growth), impaired glucose tolerance and lower pancreatic insulin content, compared with wild‐type mice." (PMID 36480511, 2023). "Additionally, mouse models with growth hormone receptor knock-out show similar phenotypes to COPD patients such as impaired glucose tolerance, decreased heart function, and reduced muscle mass." (PMID 32218378, 2020).
osteoarthritis (3 papers, 2023 to 2024). A noninflammatory degenerative joint disease occurring chiefly in older persons, characterized by degeneration of the articular cartilage, hypertrophy of bone at the margins and changes in the synovial membrane. "Acting independently of the growth hormone receptor, it can reduce inflammation‐induced damage and promote tissue repair in an animal model of osteoarthritis." (PMID 36969366, 2023).
osteosarcoma (3 papers, 2008 to 2021). A usually aggressive malignant bone-forming mesenchymal neoplasm, predominantly affecting adolescents and young adults. "Interestingly, a recent study reported the overexpression of GHR in osteosarcoma samples and that GHR gene knockdown reduced proliferation, invasion and migration while increasing apoptosis." (PMID 34484116, 2021).
Short stature (3 papers, 2015 to 2022). A height below that which is expected according to age and gender norms. "Monogenic causes of short stature which are associated with a low serum IGF-I level and normal or high GH levels could comprise the defects of GH1 (bioinactive GH), GHSR (ghrelin receptor), GHR (GH receptor), STAT5B, IGF1, and IGFALS." (PMID 26777041, 2015). "However, children with idiopathic short stature (ISS) show growth impairment without GH or GHR defects." (PMID 28557176, 2017).
Somatotropinomas (3 papers, 2016 to 2022). "In somatotropinomas, both GH/GHR and PDGF/PDGFR can synergize the signal transduction that they elicit, at least in part by virtue of GH's ability to potentiate and sustain GH signaling." (PMID 30210447, 2018). "From our series of 21 human somatotroph tumors, no mutations of GHR were found, including the p.His49Lys mutant known to impair GHR function." (PMID 27267119, 2016).
chronic kidney disease (2 papers, 2020 to 2023). Impairment of the renal function secondary to chronic kidney damage persisting for three or more months. "Past research has revealed that under the condition of different chronic kidney diseases, including DKD, the expression level of renal GHR was decreased both in humans and in rodents." (PMID 37127580, 2023).
Cirrhosis (2 papers, 2021 to 2022). A chronic disorder of the liver in which liver tissue becomes scarred and is partially replaced by regenerative nodules and fibrotic tissue resulting in loss of liver function. "In the present study, we observed that HCC patients exhibited significantly lower hepatic expression of GHR than those of cirrhosis and control groups, mostly due to hepatocellular dysfunction as a consequence of chronic liver disease, and tumor burden." (PMID 36374927, 2022).
colitis (2 papers, 2017). Inflammation of the colon. "Inflammation induced intestinal GH resistance in UC and experimental colitis by down-regulating GHR expression and up-regulating suppressor of cytokine signalling (SOCS) proteins." (PMID 28946616, 2017). "In situ hybridization targeting the GH receptor (GHR) and relevant transcriptional analyses were performed in patients with UC and in IL-10 knock-out mice with piroxicam accelerated colitis (PAC)." (PMID 28946616, 2017). "In IL-10 gene disrupted mice, experimental colitis is also characterized by reduced GHR expression in the liver driven by TNF-α-induced reduction in nuclear SP3." (PMID 28486400, 2017). "We used IL-10 k.o. mice with piroxicam accelerated colitis (PAC), to evaluate the influence of active colonic inflammation on GHR expression in vivo (see experimental setup #1 in Section 4.6)." (PMID 28946616, 2017).